PRELP (proline and arginine rich end leucine rich repeat protein)
Diseases named in the same sentence as PRELP in open-access papers (continued):
Sharing a sentence is not in itself a finding about the gene and the disease.
lung carcinoma (2 papers, 2021 to 2025). "We previously showed that PRELP exerts physiological activities, including cell growth suppression and morphological change of A549 lung carcinoma cells, at micromolar concentrations." (PMID 40634432, 2025). "RNA-seq analysis revealed that PRELP greatly promotes gene expression of various extracellular matrix (ECM) components in A549 lung carcinoma cells, also at micromolar concentration." (PMID 40634432, 2025). "For cell-based assay, we used a human lung carcinoma cell line A549, as gene expression level of PRELP is suppressed in the majority of lung cancer types." (PMID 33428936, 2021). "Furthermore, cell-based analysis using recombinant PRELP protein showed that PRELP suppressed cell growth and affected cell morphology of A549 lung carcinoma cells, also at micromolar concentration." (PMID 33428936, 2021). "In addition, we showed that the addition of micromolar concentration of recombinant PRELP to A549 lung carcinoma cells induced the suppression of cell growth and change of cell morphology." (PMID 33428936, 2021).
pancreatic cancer (2 papers, 2018 to 2025). "Furthermore, Chen and colleagues found that PRELP, LGALS1 and RPS8 might be significant prognostic factors for pancreatic cancer, while another study showed that PNMA1 was associated with prolonged overall survival and might serve as a prognostic biomarker for pancreatic cancer." (PMID 29515771, 2018).
Alzheimer disease (1 paper, 2025). A progressive, neurodegenerative disease characterized by loss of function and death of nerve cells in several areas of the brain leading to loss of cognitive function such as memory and language. "An early-onset Alzheimer’s disease study predicted potential biomarker of PRELP attaining a causal relationship with inflammatory states." (PMID 41327336, 2025).
B-cell non-Hodgkin lymphoma (1 paper, 2022). The most common type of non-Hodgkin lymphoma. "Interestingly, a subset of the members in the SLRP protein family have been previously identified in B-cell Non-Hodgkin’s lymphomas including DCN, BGN, ASPN, FMOD, LUM, PRELP, and TSKU." (PMID 36873459, 2022).
basal cell carcinoma (1 paper, 2022). A carcinoma involving the basal cells. "Interestingly, the terms “basal cell carcinoma” and “TGF-β signaling pathway” were enriched in the KEGG pathways of NPPA, OMD, and PRELP, and acted as the positive pathways." (PMID 36544902, 2022).
bladder carcinoma in situ (1 paper, 2020). Also known as carcinoma in situ of the urinary bladder or high grade intraurothelial neoplasia, this is a flat lesion of the transitional cell epithelium characterized by severe cytologic atypia. "On the other hand, we found that in the bladder epithelia, the knockout mice of OMD and/or PRELP gene caused partial EMT and a loss of tight junctions of the umbrella cells and resulted in formation of a bladder carcinoma in situ-like structure by spontaneous breakdowns of the umbrella cell layer." (PMID 33202923, 2020).
carcinosarcoma (1 paper, 2022). A malignant tumor composed of a mixture of carcinomatous and sarcomatous elements. "Next, we evaluated PRELP gene expression using clinical tissues that matched with those from the patients with ovarian cancer, including OCCC, HGSOC, low-grade serous carcinoma, and carcinosarcoma." (PMID 36556220, 2022).
colon cancer (1 paper, 2021). "Based on a search of the literature, we found that the oncogenic role of PRELP in colon cancer has been previously reported." (PMID 34157681, 2021).
cystic fibrosis (1 paper, 2018). Autosomal recessive disorder caused by pathogenic variants in the CFTR gene (cystic fibrosis transmembrane conductance regulator), which encodes a chloride and bicarbonate channel expressed in epithelial cells, and follow the diagnosis criteria. "Fluoxetine, methyldopa and sulfadiazine can inactivate cystic fibrosis trans-membrane conductance regulator and sequentially down-regulate the expression of Collagen, THBS, COMP and PRELP." (PMID 30115125, 2018).
depression (1 paper, 2020). "PRELP (Prolargin) related to neural regulation, decreased prolactin is associated with depression and insomnia." (PMID 32249904, 2020).
diabetes (1 paper, 2017). "Other diabetes-specific proteins were ApoE, Timp3, fibrillin, fibronectin, and PRELP." (PMID 29284024, 2017).
dilated cardiomyopathy (1 paper, 2025). Cardiomyopathy which is characterized by dilation and contractile dysfunction of the left and right ventricles. "Zhu’s study identified NPPA, OMD, and PRELP as biomarkers for dilated cardiomyopathy and HF using random forests." (PMID 41158506, 2025).
glioblastoma (1 paper, 2023). The most malignant astrocytic tumor (WHO grade IV). "Further, survival predictors based on gene signatures for glioblastoma obtained from microarray experiments achieved 100% accuracy if composed of Gfap, Pzprz1, Gpm6b and Prelp transcripts suggesting that PRELP is involved in extracellular matrix (ECM) remodeling in glioblastoma." (PMID 36818562, 2023).
hepatic cirrhosis (1 paper, 2020). "PRELP mRNA expression was significantly down-regulated in HCCs compared with that in adjacent NTs or hepatic cirrhosis in 10 out of the 15 datasets." (PMID 33033521, 2020). "In this study, we compared PRELP mRNA expression levels between HCCs and adjacent normal tissues (NTs) or hepatic cirrhosis by analyzing several public datasets." (PMID 33033521, 2020). "In our study, we demonstrated that PRELP was generally down-regulated in HCC tissues in comparison with matched NTs or hepatic cirrhosis." (PMID 33033521, 2020).
leukemia (1 paper, 2014). A malignant (clonal) hematologic disorder, involving hematopoietic stem cells and characterized by the presence of primitive or atypical myeloid or lymphoid cells in the bone marrow and the blood. "Although, these are relatively understudied genes, PRELP and MIER1, both are associated with leukemia." (PMID 24947164, 2014).
mantle cell lymphoma (1 paper, 2013). Mantle cell lymphoma is a rare form of malignant non-Hodgkin lymphoma affecting B lymphocytes in the lymph nodes in a region called the ``mantle zone''. "PRELP was expressed (RT-PCR) in all CLL patients (30/30), as well as in some patients with mantle cell lymphoma (3/5), but not in healthy donor leukocytes (0/20) or tumor samples from other hematological malignancies (0/35)." (PMID 23826326, 2013).
metastatic colorectal cancer (1 paper, 2025). "We identified a specific population of PRELP+ CAFs enriched in liver metastatic colorectal cancer (mLC), which were inversely correlated with patient prognosis." (PMID 41031085, 2025).
metastatic melanoma (1 paper, 2023). A melanoma that has spread from its primary site to another anatomic site. "The number of tumor-infiltrating B cells and tumor PRELP expression were associated with a decreased risk of skin cutaneous melanoma (HR = − 2.533; p = 2.81E−02), which was not significant for metastatic melanoma (HR = − 1.995; p = 1.25E−01)." (PMID 37730606, 2023). "High expression of PRELP in tumors correlated with a high number of tumor-infiltrating CD8+ T cells in skin cutaneous (HR = − 4.079, p = 1.25e−04) and metastatic melanoma (HR = − 3.758; p = 6.19e−04)." (PMID 37730606, 2023).
metastatic tumors (1 paper, 2025). "Together, these findings highlight the intrinsic regulatory mechanisms underlying the diverse functions of PRELP+ CAFs, emphasizing their dual roles in stromal remodeling and immunosuppressive regulation within the metastatic tumor microenvironment." (PMID 41031085, 2025). "Pseudotime trajectory analysis further suggested that PRELP+ CAFs represent a terminally differentiated state of fibroblasts within liver metastatic tumors, underscoring their role in remodeling the TME to facilitate metastatic progression." (PMID 41031085, 2025). "Pseudotime trajectory analysis suggested that PRELP+ CAFs represent the terminal differentiation state of fibroblasts within liver metastatic tumors." (PMID 41031085, 2025).
myeloma (1 paper, 2013). "Thereafter, we tested cell lines and found that PRELP mRNA was expressed in all four CLL cell lines (EHEB, I83-E95, 232-B4, WAC3-CD5) but not in cell lines derived from myeloma (0/1), T cell leukemia (0/1), ALL (0/4), AML (0/1), CML (0/1), and NK cell lymphoma (0/1)." (PMID 23826326, 2013).
myopia (1 paper, 2022). "Since PRELP is highly expressed in sclera and regulated EMT, PRELP might be aassociated with myopia." (PMID 36230849, 2022).
osteoporosis (1 paper, 2025). A condition of reduced bone mass, with decreased cortical thickness and a decrease in the number and size of the trabeculae of cancellous bone (but normal chemical composition), resulting in increased fracture incidence. "Another study demonstrated the anti-osteoporosis activity of Rb1 in dexamethasone (DEX)-induced osteoporosis rat model by regulating aryl hydrocarbon receptor (AHR)/proline/arginine-rich end leucine-rich repeat protein (PRELP)/NF-κB signaling pathway." (PMID 40507179, 2025).
ovarian carcinoma (1 paper, 2022). A malignant neoplasm originating from the surface ovarian epithelium. "To investigate the association between the PRELP mRNA expression and genomic aberrations, we first analyzed the correlation between PRELP gene expression and somatic mutations and copy number aberrations (CNAs) using a comprehensive genomic dataset of patients with ovarian cancer." (PMID 36556220, 2022). "We found that PRELP mRNA expression was significantly repressed in both primary and recurrent ovarian cancers compared with that in normal tissues (p < 0.0001)." (PMID 36556220, 2022). "We first showed that the PRELP gene expression is repressed using public datasets of clinical tissues from patients with ovarian cancer compared with normal tissues." (PMID 36556220, 2022). "PRELP mRNA expression was significantly repressed in ovarian cancer tissues by approximately 1/100th compared with that in normal tissues (p < 0.01)." (PMID 36556220, 2022).
pancreatic ductal adenocarcinoma (1 paper, 2020). An infiltrating adenocarcinoma that arises from the epithelial cells of the pancreas. "A previous study suggested low PRELP (proline/arginine-rich end leucine-rich repeat protein) expression was associated with poor patient survival in pancreatic ductal adenocarcinoma (PDAC)." (PMID 33033521, 2020).
preeclampsia (1 paper, 2023). Preeclampsia is a hypertensive disorder of pregnancy that is characterized by new-onset hypertension with proteinuria presenting after 20 weeks of gestation, and depending on mild or severe forms may initially present with severe headache, visual disturbances, and hyperreflexia. "Lumican and PRELP exist in both healthy patients and preeclampsia patients, while IGFBP-1 only exists in the tissues of preeclampsia patients and may be associated with the development of preeclampsia." (PMID 37670392, 2023). "Three S100A6-interacting proteins, lumican, PRELP, and insulin-like growth factor binding protein 1 (IGFBP-1), were found in the extracellular matrix of Wharton’s jelly in healthy and preeclampsia patients." (PMID 37670392, 2023).
retinal degeneration (1 paper, 2024). Degeneration of the retina. "In RPE, several proteins associated with retinal degeneration were downregulated (e.g., TIMP3, RDH5, PRELP)." (PMID 38605034, 2024).
Retinal dysplasia (1 paper, 2022). Abnormal growth and differentiation, structure and appearance of the retina present from birth. "Deletion of PRELP in mice resulted in retinal dysplasia associated with enhanced proliferation." (PMID 36230849, 2022). "Furthermore, deletion of PRELP in mice clearly leads to retinal dysplasia and down regulation of many adhesion-related biological events." (PMID 36230849, 2022).
rheumatic diseases (1 paper, 2020). "Studies for PRELP in human diseases are limited at present, most of which focus on rheumatic diseases." (PMID 33033521, 2020).
skin cancer (1 paper, 2023). "By comparison of the HLA-A expression in 133 skin cancer cell lines (GENT2—skin cancer cell lines) with PRELP, a significant positive correlation, Pearson correlation coefficient, r = 0.37 and p = 1.98E−09." (PMID 37730606, 2023).
tumor (18 papers, 2011 to 2025). "As a tumor suppressor in solid tumors, PRELP was associated with the occurrence and development of various cancers." (PMID 39507711, 2024). "To assess the potential role of OMD and PRELP as diagnostic markers, we set cutoff values to distinguish tumor samples from normal tissues through calculation of the interquartile range." (PMID 33202923, 2020). "These ECM-related genes are essential for remodeling the tumor microenvironment and reinforcing the matrix-forming characteristics of PRELP+ CAFs." (PMID 41031085, 2025). "Our scRNA-seq analysis identified a distinct PRELP-positive cancer-associated fibroblast (CAF) subtype that is associated with liver metastasis and tumor progression." (PMID 41031085, 2025). "Stratification based on these scores revealed that high PRELP+ CAF levels were significantly associated with poorer overall survival, suggesting that PRELP+ CAFs play a significant role in tumor progression and advancement." (PMID 41031085, 2025). "We characterize PRELP+ CAFs as a specialized, terminally differentiated fibroblast population that contributes to immunosuppression and tumor progression, highlighting them as a potential therapeutic target for inhibiting metastatic advancement." (PMID 41031085, 2025). "RNA-seq analysis also showed great up-regulation of the gene expression levels of many proteins related to cell adhesion, suggesting that PRELP exerts the tumor suppressive function through the regulation of cell adhesion." (PMID 40634432, 2025). "ADIRF, tumor-associated genes CLU, FAM13C, as well as NGF, PRELP, RERG, PTGIS, GPC3 genes were among the top 20 overexpressed genes in EcE stromal cell population." (PMID 39169201, 2024). "There exists increasing evidence about the clinical relevance of PRELP as a tumor suppressor in solid tumors and its use as a prognostic marker." (PMID 37730606, 2023). "Based on the activity of PRELP on tumor cell function described in this study, this SLRP is suggested as a candidate for anti-cancer therapy." (PMID 37730606, 2023). "We previously demonstrated that PRELP is widely downregulated in various cancers and our in vivo and in vitro analysis revealed PRELP as a novel tumor suppressor and regulator of EMT." (PMID 36230849, 2022). "Levels of PRELP mRNA are downregulated in many types of cancer, and PRELP has been reported to have suppressive effects on tumor cell growth, although the molecular mechanism has yet to be fully elucidated." (PMID 33428936, 2021). "Our result indicates that OMD and PRELP function as tumor-suppressing proteins through inhibiting EMT." (PMID 33202923, 2020). "The correlation analyses revealed that PRELP expression was relevant to later p-stages (p= 0.028) and tumor size (p= 0.001)." (PMID 33033521, 2020). "From former studies we made a conjecture that PRELP inhibits HCC progression by interacting with integrin family members within the tumor microenvironment." (PMID 33033521, 2020). "The expression of PRELP mRNA was tested by RT-PCR in tumor cells from CLL patients and other hematological malignancies as well as in PBMC and leukocyte subsets from healthy control donors." (PMID 23826326, 2013). "Recent gene-expression profiling in BC identified PRELP among the PG genes whose decreased expression correlates with enhanced tumour aggressiveness and poorer survival, suggesting that PRELP acts as a stromal tumour-suppressive factor modulating ECM integrity and TGFβ-dependent signalling." (PMID 41463344, 2025). "Given that recent studies revealed that PRELP interacts with several growth factors including transforming growth factor β1 (TGFβ1) involved in signal transduction in cancer, PRELP is expected to suppress tumor cell growth triggered by the multi-specific ligand binding." (PMID 40634432, 2025).
tumor (continued). "During the ECM degradation process, local concentrations of PRELP that were anchored to the ECM would be reduced, which might result in disruption of low affinity interactions and tumor suppressive functions of PRELP." (PMID 40634432, 2025). "Our findings support this notion, suggesting that PRELP+ CAFs may be involved in establishing an immune-tolerant niche that allows tumor cells to evade immune surveillance and promote metastasis." (PMID 41031085, 2025). "Additionally, we identified key transcription factors that regulate tumor progression in PRELP+ fibroblasts." (PMID 41031085, 2025). "Cellular communication analysis showed that PRELP+ CAFs were a highly signaling-active cell type in mLCs, suggesting that they play an important role through strong interactions with other cell types in the tumor microenvironment." (PMID 41031085, 2025). "We also validated PRELP expression in radiotherapy tumor tissue." (PMID 39507711, 2024). "Furthermore, low levels of PRELP expression were associated with a low T cell infiltration and low HLA class I expression suggesting that an impaired PRELP expression of tumor cells represents an immune escape phenotype." (PMID 37730606, 2023). "This is in line with recent reports demonstrating a tumor inhibitory capacity of PRELP, which might be at least partially due to its ability to directly bind TGFB1." (PMID 37730606, 2023). "Based on these results, a tumor-suppressive activity of PRELP in tumor cells has been suggested." (PMID 37730606, 2023). "Next to its physiological function, PRELP has been reported as a biomarker in different human cancers, but its role is controversially discussed dependent on the tumor type analyzed regarding its correlation with the patients’ survival and prognostic potential." (PMID 37730606, 2023). "PRELP may have a fundamental role in the microenvironment and seems to function as a novel type of a tumor suppressor against RB." (PMID 36230849, 2022). "However, proteomic analysis of CC structures, readily accessible form the tumor vasculature, has described the existence of a reduction in PRELP expression." (PMID 34440771, 2021). "Therefore, we particularly focused on growth factor receptors coprecipitated with PRELP, which would be key proteins to explain molecular function of PRELP as tumor suppressor." (PMID 33428936, 2021). "Furthermore, patients who had low tissue expression levels of PRELP tended to have larger tumor size and advanced pathological stage." (PMID 33033521, 2020). "To confirm it, we performed KEGG pathway analyses on the GSEA platform and the results suggested that high expression of PRELP was positively related to gene sets extracellular matrix receptors and cell adhesion which are main pathways in tumor microenvironment." (PMID 33033521, 2020). "However, cases with low PRELP expression tended to have advanced p-stages (p=0.028) and larger tumor size (p=0.001)." (PMID 33033521, 2020). "First, while the association between PRELP+ CAF abundance and poor prognosis is statistically significant, this correlation does not establish causation, and residual confounding from clinical or tumor microenvironmental variables may influence these findings." (PMID 41031085, 2025). "Our findings indicate that the APP and collagen signaling pathways mediated by PRELP+ CAFs may inhibit immune cell function, promote immune evasion by tumor cells, remodel the ECM, and influence immune cell infiltration and activity through the APP-CD74 and collagen-CD44 axes." (PMID 41031085, 2025). "Finally, to reveal the role of PRELP, we conducted in vitro experiments and found that PRELP may function as a tumor suppressor in CRC." (PMID 39247594, 2024). "Transcriptomically, PRELP+ CAFs exhibit a unique signature defined by extracellular matrix components (e.g., PRELP, COLEC11, ITGBL1) and the activation of pro-tumor pathways such as TGF-β and Wnt signaling." (PMID 41031085, 2025).